CRP (C-reactive protein)
Diseases named in the same sentence as CRP in open-access papers (continued):
Sharing a sentence is not in itself a finding about the gene and the disease.
myocardial infarction (continued). "Point-of-care tests also detected cardiac damage in 91% of prehospital acute myocardial infarction-patients and the CRP test has been considered an important tool in assisting the care continuum of patients." (PMID 34968343, 2021). "Clear evidence has been shown in previous clinical studies, investigating CRP apheresis after myocardial infarction, that CRP depletion reduces systemic inflammation and cardiac tissue damage." (PMID 34408751, 2021). "The accuracy of CRP/troponin ratio levels measured early on presentation in STEMI with or without NSTEMI patients for distinguishing myopericarditis from myocardial infarction." (PMID 33886564, 2021). "Another was an ICU patient with myocardial infarction with increased C-reactive protein and procalcitonin of unclear etiology." (PMID 34605900, 2021). "Elevated levels of inflammatory biomarkers such as C-reactive protein (CRP), interleukin-6 (IL-6), or tumor necrosis factor (TNF) have been shown to be associated with an increased risk of myocardial infarction and mortality." (PMID 33481059, 2021). "Canakinumab, an interleukin-1b inhibitor, has been considered to have a dose-dependent reduction in the occurrence of heart failure in patients with prior myocardial infarction and elevated CRP." (PMID 34884196, 2021). "In the clinical model prior myocardial infarction (OR = 3.31, 95% CI = 1.37–8.12, p = 0.008), SpO2 (OR = 0.94, 95% CI = 0.89–0.98, p = 0.005) and CRP (OR = 1.95, 95% CI = 1.51–2.58, p < 0.001) remained statistically significant." (PMID 34842822, 2021). "Inhibition of IL-1B signalling has been shown to have an anti-tumour effect in the CANTOS trial, in that patients with previous myocardial infarction and high C-reactive protein levels assigned to receive Canakinumab, displayed reduced lung cancer mortality." (PMID 34290237, 2021). "In contrast, myocardial infarction is characterized by elevated troponin with a relatively lower increase in CRP levels." (PMID 33886564, 2021). "Elevated levels of inflammation, as determined by CRP, have been associated with poor outcomes after myocardial infarction, but a rise in CRP levels after myocardial infarction is usually delayed, peaking after 50 h." (PMID 33721106, 2021). "Changes in CRP concentrations during myocardial infarction are considered to play a crucial role regarding adverse cardiovascular events, including death and LV dysfunction, even years later." (PMID 34884196, 2021). "Plasma concentrations of IL-6 and hs-CRP (inflammation markers) have predictive value for the prognosis of patients with myocardial infarction." (PMID 34231707, 2021). "Ischemic stroke and myocardial infarction are well known to show inflammatory pathways in the acute and subacute stages, with elevated CRP levels." (PMID 33532130, 2021). "Among several inflammatory markers in the setting of myocardial infarction, CRP represents the most intensively explored marker." (PMID 34884196, 2021). "The phagocytosis of ischemic/hypoxic cells in the setting of acute myocardial infarction activates IL-6 production, which further induces more CRP, amplifying the immune response." (PMID 34707513, 2021). "Recurrent myocardial infarction and cardiovascular death are strongly related to CRP increases during acute coronary syndrome." (PMID 33628645, 2021). "CAMI-1 shows a pronounced dose-response relationship between CRP concentration and myocardial infarction damage in the control cohort." (PMID 33778017, 2021). "To date, most promising results have been obtained from clinical trials involving canakinumab—targeted interleukin-1ß in patients with previous MI (myocardial infarction) and a high sensitivity CRP ≥ 2 mg/l." (PMID 33479786, 2021). "Some previous studies also found that CRP was predictive for the occurrence of HF in stable myocardial infarction survivors or in patients with STEMI or AMI." (PMID 34109224, 2021).
myocardial infarction (continued). "C-reactive protein and n-3 fatty acids in patients with a previous myocardial infarction: a placebo-controlled randomized study." (PMID 33566983, 2021). "A recent trial enrolled ACS patients with previous myocardial infarction according to baseline serum levels of the inflammatory marker C-reactive protein ≥2 mg/L, which had been previously shown to predict adverse outcomes." (PMID 33919478, 2021). "The serum CRP level in acute myocardial infarction (AMI), unstable angina, and stable angina pectoris is higher than that in non-CAD patients." (PMID 34900087, 2021). "These pre-clinical studies had shown a significant positive influence of CRP apheresis on myocardial infarct size and LV function as determined by CMR and macroscopic analyses." (PMID 33778017, 2021). "Our results are in line with previous studies regarding the predictive role of prior myocardial infarction, immunodeficiency and increasing CRP levels." (PMID 34842822, 2021). "The observed dose-response relationship between CRP concentrations and myocardial infarct size and its beneficial modulation by CRP apheresis establishes a fundamental, innovative approach for the treatment of STEMI." (PMID 33778017, 2021). "More than 10,000 patients with previous myocardial infarction and CRP levels > 2 mg/L, were randomized to receive placebo or three different subcutaneous doses of canakinumab every 3 months (50 mg, 150 mg, and 300 mg)." (PMID 34198968, 2021). "CRP elimination significantly reduced the necrotic zone in animal models ofacute myocardial infarction." (PMID 35127146, 2021). "The idea of studying it within the pathophysiology of acute myocardial infarction is related to the role of inflammation in atherothrombosis and to CRP synthesis by hepatocytes, as a result of stimulation by inflammatory cytokines, primarily by IL-6." (PMID 33238444, 2020). "In experimental models of myocardial infarction, an overexpression of CRP demonstrated greater left ventricular dysfunction, while an inhibition of exogenous CRP with a specific antagonist or apheresis decreased infarct size." (PMID 31991903, 2020). "Research on myocardial infarction searched C-reactive protein, myoglobin, myeloperoxidase, creatine phosphokinase, creatin kinase MB, cardiac troponin T and cathepsin-L, all reporting statistically significant result." (PMID 32040469, 2020). "Conversely, the use of IL-1ß inhibitor (canakinumab) showed promising results in patients with myocardial infarction and a blood level of C-reactive protein of 2 mg/L or more despite aggressive secondary prevention strategies." (PMID 33195306, 2020). "The role of miR-21 in inflammation and its relation with CRP is emphasized by the fact that both elevated circulating miR-21 and increased CRP-levels after myocardial infarction are predictive of left ventricular remodelling." (PMID 32537679, 2020). "Gabriel AS, Martinsson A, Wretlind B, Ahnve S. IL-6 levels in acute and post myocardial infarction: their relation to CRP levels, infarction size, left ventricular systolic function, and heart failure." (PMID 32876202, 2020). "Endpoints were safety, myocardial infarct size and function as well as CRP concentration in patients with acute STEMI." (PMID 32932587, 2020). "CRP blood concentration increases during injury, autoimmune disease, and heart attack but also during bacterial, viral, and fungal infections." (PMID 32092918, 2020). "In light of these findings our study gains importance as it provides an explanation for the rise in CRP-levels after myocardial infarction." (PMID 32537679, 2020). "Peak circulating levels of CRP after myocardial infarction correlate with infarct size, development of heart failure, and mortality." (PMID 32537679, 2020). "CRP is a protein that increases in the serum with infection, inflammation surgery, heart attack, other heart disease, and trauma." (PMID 32642445, 2020).
myocardial infarction (continued). "The transition of CRP mainly takes place in injured tissue and seems to contribute to ischemia and reperfusion injuries, including myocardial infarction." (PMID 33080990, 2020). "The upregulation of two inflammatory biomarkers (C-reactive protein and soluble tumor necrosis factor receptor II) and its association with the progression of CKD have been observed in a large cohort of patients with myocardial infarction–induced CKD." (PMID 33353159, 2020). "More recently it has been found that microvesicles from patients after myocardial infarction can convert pentameric CRP into pro-inflammatory monomeric CRP." (PMID 32537679, 2020). "CRP levels are significantly increased in cardiovascular patients without any symptoms, obvious cardiovascular disease, unstable angina pectoris, myocardial infarction, and other diseases." (PMID 33008437, 2020). "CRP apheresis has been applied successfully in a controlled multi-center trial in patients with myocardial infarction (CAMI-1 trial)." (PMID 32932587, 2020). "The predictive value of markers like C-reactive protein (CRP) and interleukin (IL)-6 in determining the risk of myocardial infarction is well-documented." (PMID 30726210, 2019). "Myocardial infarction is an inflammatory pathology, and in the presence of B. longum R0175, the plasma CRP concentrations were reduced compared to the Lactobacillus strains tested." (PMID 31009477, 2019). "Prognosis of myocardial infarction tends to be worse when serum C-reactive protein (CRP) level is high." (PMID 31063484, 2019). "Phospholipase A2-dependent dissociation of circulating pentameric CRP (pCRP) to monomeric CRP (mCRP) localized and aggravated inflammation in AS and myocardial infarction." (PMID 30761006, 2019). "C-reactive protein (CRP) was chosen as the model target for the biosensor as it is an important marker of inflammation and can also predict myocardial infarction and sudden cardiac death." (PMID 30959878, 2019). "The CANTOS trial, for instance, involved over 10,000 patients with a previous myocardial infarction and high levels of C-reactive protein." (PMID 30935055, 2019). "Other reports evidenced significantly higher levels of CRP and IL-6 in the patients with unstable angina and myocardial infarction, supporting the connection between acute coronary syndromes and inflammatory status." (PMID 31590380, 2019). "An epidemiological survey showed the incidence of acute stroke in patients with high hyper-sensitive C-reactive protein (hs-CRP) level was two times higher than healthy people and myocardial infarction was three times higher." (PMID 29739462, 2018). "Recent studies indicated that CRP is directly involved in cardiovascular diseases, and is the most reliable predictor of cerebral congestion and myocardial infarction." (PMID 29601593, 2018). "Including over 10,000 patients with high CRP levels who had had a previous myocardial infarction and were studied over 4 years, this trial showed a significantly lower rate of recurrent cardiovascular events as well as reduced CRP levels." (PMID 30165816, 2018). "Canakinumab, a monoclonal antibody (mAb) directed against interleukin-1β (IL-1β), significantly reduced adverse CV outcomes in patients with a history of myocardial infarction (MI) and elevated C-reactive protein (CRP)." (PMID 29755478, 2018). "Previous study on serum leptin, IL-6 and hs-CRP levels have been conducted in acute myocardial infarction (AMI) patients from south India (Chennai)." (PMID 30001365, 2018). "The deterioration in the coronary flow reserve has been observed with the growth of high sensitivity CRP (hs-CRP), which induces inflammation in the myocarditis or in acute myocardial infarction." (PMID 30314292, 2018). "Administration of isolated pure human CRP to rats following ligation of the coronary artery substantially increased the size of the resulting myocardial infarct and human CRP was co-deposited with rat complement on and around the infarcted tissue." (PMID 30459761, 2018).
myocardial infarction (continued). "CRP is capable of predicting adverse cardiovascular damage such as myocardial infarction, ischemic stroke and sudden cardiac mortality." (PMID 29534446, 2018). "Again, anakinra significantly reduced CRP levels 72 h after myocardial infarction; after 10–14 weeks, this reduction in CRP correlated with a reduction in left ventricular end-systolic volume." (PMID 30459597, 2018). "Nevertheless, low correlations of S100A8/A9 levels in serum with CRP and leukocytes were detectable in patients with tonsillitis which is in concordance with recent findings in patients with myocardial infarction or rheumatoid arthritis." (PMID 29180834, 2017). "Levels of suPAR showed an increase of 15% following acute myocardial infarction, compared with a 365% increase in hs-CRP levels." (PMID 29109596, 2017). "Prior reports have shown that CRP gradually increased during the first 48h after myocardial infarction." (PMID 29166391, 2017). "Patients with raised C-reactive protein and a normal erythrocyte sedimentation rate usually have infection but some have other tissue damage (e.g., myocardial infarction or venous thromboembolism)." (PMID 29138696, 2017). "Levels of plasminogen activator inhibitor, interleukin 6, and C-reactive protein in patients with myocardial infarction on day 1 and 12 of hospitalization." (PMID 27725801, 2016). "Further, administration of a specific small-molecule inhibitor of CRP to rats undergoing acute myocardial infarction abrogated the increase in infarct size and cardiac dysfunction produced by injection of human CRP." (PMID 27258004, 2016). "Acute myocardial infarction was predicted by a combination of electrocardiogram and CRP levels with 80.0% sensitivity and 100% specificity." (PMID 27585820, 2016). "In other studies, a predictor of cardiovascular events was assessed by elevation of C reactive protein level (a marker of myocardial infarction) upon exposure to PM." (PMID 25653681, 2015). "CRP is an acute-phase protein that increases during the host response to tissue injuries, including infection, trauma, surgery, myocardial infarct, and cancer." (PMID 25999661, 2015). "Significantly lower adiponectin levels together with increased CRP levels were demonstrated in a group of patients with myocardial infarction." (PMID 26074960, 2015). "It is well accepted that circulating biomarkers, including C-reactive protein and interleukin-6, reliably predict major cardiovascular events, including myocardial infarction or death." (PMID 25960621, 2015). "Another prospective cohort study of 50 PD patients with 3-year follow-up after the initial determination of CRP and showed that an elevated plasma CRP (>6.0 mg/L) was predictive of myocardial infarction (HR 4.8)." (PMID 25961883, 2015). "We also found and replicated biallelic combinations of TGFB1 with FGB, TGFB1 with CRP and IFNG with PTGS1 genetic variants associated with myocardial infarction providing a detectable cumulative effect." (PMID 26658659, 2015). "Previous data has shown that there is a strong relationship between Hs-CRP levels in myocardial infarction (AMI) patients and unstable angina pectoris (UAP) patients." (PMID 25822970, 2015). "A contribution of CRP to pathogenesis has been suggested for two other cardiovascular disease entities, that is, myocardial infarction and dilated cardiomyopathy." (PMID 24799767, 2014). "The RA+CVD group had increased levels of inflammatory biomarkers i.e., CRP, history of myocardial infarction and use of oral steroids, Cox2 inhibitors and disease-modifying anti-rheumatic drugs." (PMID 24874661, 2014). "In a study of acute myocardial infarction patients, it was reported that insulin infusion attenuated the rise of CRP and enhanced fibrinolysis." (PMID 24563867, 2014).
myocardial infarction (continued). "Studies in animals (mice, rats, and rabbits) and human specimens have shown that both CRP and components of the activated complement system are deposited and colocalized in myocardial infarcts and that complement activation is due to the presence of CRP." (PMID 24948846, 2014). "CRP is a reactive protein in the acute phase response, which is observed at increased levels in a number of ailments, including tissue damage, myocardial infarction and malignant tumors." (PMID 25009608, 2014). "The purpose of administering a PCh-based compound to target CRP is to inhibit binding of CRP to damaged cells to prevent further damage to myocardial infarcts." (PMID 24948846, 2014). "CRP plasma levels significantly rise after myocardial infarction indicating the human body's acute phase response." (PMID 24799767, 2014). "Mostly by employing animal models of I/R injury, it has been shown that CRP enhances the size of myocardial infarcts and also contributes to ischemic tissue damage in intestine, lung, kidney, and brain." (PMID 24948846, 2014). "CRP has been shown to exacerbate left ventricular dysfunction and promote adverse left ventricular remodeling after myocardial infarction." (PMID 24948846, 2014). "While these results are disappointing to CRP believer, this study cannot exclude the possibility that CRP participates in other pathological processes such as thrombosis, myocardial infarction, and arthritis." (PMID 24872599, 2014). "An elevated CRP level has been reported to be an independent predictor of myocardial infarction and cardiovascular mortality in PD patients." (PMID 24667814, 2014). "In case of acute myocardial infarction in model animals, CRP worsens an already existing disease; CRP does what it is programmed to do, that is, to bind to PCh and activate complement, and just in this case CRP does harm." (PMID 24948846, 2014). "Further, aggregated and/or ligand-complexed CRP can be pro-inflammatory and is co-deposited with activated complements in all acute myocardial infarction lesions." (PMID 25392798, 2014). "Serum level of CRP was significantly higher while apoA level was profoundly lower in the acute myocardial infarction when compared to the table angina group (p < 0.05)." (PMID 25477191, 2014). "On the other hand, the PCh-binding function of CRP is detrimental if it occurs on injured host cells because it causes more damage to the tissue via complement activation; this is how CRP worsens acute myocardial infarction and ischemia/reperfusion injury." (PMID 24948846, 2014). "The circulating levels of C-reactive protein (CRP), tumor necrosis factor-α (TNF-α), and interleukin-6 (IL-6) are positively correlated with the risk of primary and recurrent myocardial infarction and death." (PMID 24192015, 2013). "This is partially because CHD can cause ischemia and hypoxia, which leads to local tissue damage, myocardial infarction, myocardial fibrosis and necrosis, and neutrophil infiltration, thus stimulating the production of CRP." (PMID 24148690, 2013). "CRP is mainly produced by hepatocytes and known for its systemic response to excessive vascular events, such as myocardial infarction." (PMID 24060373, 2013). "There is also some evidence for complement activation by CRP in acute injury, such as myocardial infarction." (PMID 24167754, 2013). "Inflammatory response following acute myocardial infarction has been well documented since the 1940s and 1950s, including increased erythrocyte sedimentation rate, the C-reactive protein analysis, and the determination of serum complement." (PMID 23819098, 2013). "Acute myocardial infarction (MI) provokes a systemic inflammatory response with a release of pro-inflammatory cytokines and enhanced synthesis of C-reactive protein (CRP)." (PMID 22446726, 2012). "High-sensitivity CRP (hs-CRP) rises acutely after tissue injury, including myocardial infarction (MI)." (PMID 24049653, 2012).